SNAI3-AS1 (SNAI3 antisense RNA 1)
Synonyms: MGC23284
Gene: Long non-coding RNA gene on chromosome 16 (88,663,298 to 88,687,289, forward strand). Ensembl gene ENSG00000260630.
Diseases named in the same sentence as SNAI3-AS1 in open-access papers:
SNAI3-AS1 is named in the same sentence as 1 disease in open-access papers, as found by Europe PMC text mining. Sharing a sentence is not in itself a finding about the gene and the disease. The quoted sentences say what the papers report.
tumour (1 paper, 2019). "Therefore, our finding indicated that SNAI3‐AS1 may act as a tumour oncogene in HCC." (PMID 31264769, 2019).